CXCL1 (C-X-C motif chemokine ligand 1)
Diseases named in the same sentence as CXCL1 in open-access papers (continued):
Sharing a sentence is not in itself a finding about the gene and the disease.
colorectal cancer (continued). "CXCL1 supports breast, bladder, and colorectal cancer cell survival under chemotherapy." (PMID 40076892, 2025). "Furthermore, miR-302e targets CXCL1 to modulate cell proliferation, invasion, and apoptosis of colorectal cancer." (PMID 38955795, 2024). "There is elevated CXCL1 expression in colorectal cancer tumors compared to healthy tissue." (PMID 37408240, 2023). "Elevated CXCL1 expression in colorectal cancer cells may also be the result of high basal NF-κB activation associated with the overexpression of UEV1A, an enzyme that catalyzes poly-ubiquitination, which results in the activation of NF-κB." (PMID 37408240, 2023). "In colorectal cancer, CXCL1 is produced by a variety of cells." (PMID 37408240, 2023). "CXCL1 also affects cells in the tumor niche in colorectal cancer." (PMID 37408240, 2023). "Similarly, we found recently that apoptotic colorectal cancer cells secrete CXCL1, CXCL5, and CXCL8 in response to chemotherapeutic drugs such as oxaliplatin, 5-FU, or bortezomib." (PMID 37957750, 2023). "CXCL1 in colorectal cancer tumors participates in tumorigenic processes." (PMID 37408240, 2023). "An elevated CXCL1 expression in a colorectal cancer tumor may also be due to hypoxia-inducible factor-2 (HIF-2) which has been shown to be responsible for the expression of CXCR2 ligands in colorectal tumors in a murine model." (PMID 37408240, 2023). "The upregulated expression of CXCL1 has been validated in colorectal cancer patients." (PMID 36434686, 2022). "It was found that CXCL1 was a direct target of miR-302e on cell proliferation, migration, invasion, and apoptosis in colorectal cancer, and the mechanism was correlated with CXCL1 expression regulated by miR-302e and the inactivation of the JAK-STAT signaling pathway." (PMID 35770088, 2022). "For example, EMT-mediated CXCL1/5 can modulate resistance to anti-EGFR therapy in colorectal cancer, and CXCL1/5 may be a potential serum biomarker for predicting colorectal cancer resistance to EGFR therapy." (PMID 36393968, 2022). "Therefore, CXCL1 is a potential prognostic biomarker and therapeutic target in the context of colorectal cancer." (PMID 36434686, 2022). "For example, in colorectal cancer, CXCL1, 2, and 5 are parallelly increased in tumorigenesis." (PMID 35332119, 2022). "In addition, CXCL1 produced in primary colorectal cancer cells was shown to form a pre-migratory ecology by recruiting MDSCs to eventually promote liver metastasis." (PMID 36434686, 2022). "We found that CXCL1 promotes the proliferation, migration, and invasion of colorectal cancer cells." (PMID 36434686, 2022). "In colorectal cancer patients, CXCL1 also showed a positive correlation with VEGF expression." (PMID 36434686, 2022). "Therefore,it is of interest to document the molecular docking analysis of antimicrobial peptides with the CXCL1 protein target for colorectal cancer." (PMID 34092958, 2021). "Hence, we report the molecular docking analysis ofantimicrobial peptides MREEKKERKRD and MVQGAKRGGRLHRV with the target protein CXCL1 in the context of colorectal cancer for further consideration in drug discovery." (PMID 34092958, 2021). "Similarly, CXCL1 was also reported to promote neoangiogenesis in breast, liver, and colorectal cancers." (PMID 33463063, 2021). "Down-regulation of CXCL1 inhibited liver metastasis of colorectal cancer." (PMID 31438997, 2019). "Finally, CXCL1, a CXCR2 ligand, was inversely associated with recurrence-free survival in colorectal cancer patients." (PMID 24376747, 2013). "Thus, we observed for the expression levels of CXCL8, CXCL1 and CXCL5 a significant association with the development of colorectal carcinoma and also CRLM." (PMID 18578857, 2008). "However, serum CXCL1 levels are reduced in patients with colorectal cancer." (PMID 37408240, 2023).
colorectal cancer (continued). "Recently, evidence suggests that CXCL1 secreted from tumor through the paracrine or autocrine mechanisms attracted various inflammatory cells or stromal cells into the tumoral microenvironment promoting tumor growth and metastasis, such as bladder, lung, and liver metastasis colorectal cancer." (PMID 34760697, 2021). "CXCL1 secretion could enhance the invasion and metastasis of several types of cancer cells; in contrast, silencing or knockdown of CXCL1 could inhibit tumor growth in hepatocellular carcinoma and colorectal cancer liver metastasis." (PMID 34760697, 2021). "Furthermore, the chemokine CXCL1 was demonstrated to promote angiogenesis in colorectal cancer." (PMID 28938014, 2017). "Other studies reported that the microbiota was closely related to immunity and inflammation; e.g., Fusobacterium nucleatum facilitated IL‐8 and CXCL1 excretion, thereby inhibiting HCT116 (human colorectal carcinoma) cell proliferation and migration." (PMID 39754314, 2025). "The CXCL1/CXCR2 and CXCL8-CXCR1/CXCR2 axes are under intensive investigation as they appear to regulate the progression and invasion of colorectal cancer (CRC)." (PMID 37509572, 2023). "In addition, CXCL1 may also be a marker of early-stage colorectal cancer." (PMID 37408240, 2023). "In this study, we conducted differential gene expression analysis on three GEO datasets and confirmed SPP1, MMP1, CXCL8, CXCL1, TIMP1, MMP3, and CXCL10 as core regulatory genes in colorectal cancer through a protein-protein interaction network." (PMID 37842645, 2023). "For example, SMAD4 expression is reduced in colorectal cancer cells, as it interferes with the action of TGF-β, and thus leads to an increase in CXCL1 expression in the cancer cell." (PMID 35054978, 2022). "Colorectal CSCs secrete CXCL1 and CXCL2 to attract neutrophils, which promoted tumorigenesis of colorectal cancer cells via interleukin-1β." (PMID 31998654, 2019). "Several research groups reported that CXCL1 and CXCR2 were poor prognostic factors in studies using human samples of several types of cancers including gastric cancer, colorectal cancer, and pancreatic cancer." (PMID 28575019, 2017). "Levels of CCL2, CXCL1 and CXCL5 were consistently higher than those of VEGF (a current therapeutic target in colorectal cancer) in all patients examined." (PMID 22125641, 2011). "Our study also showed that our colorectal cancer patients explant tissue secreted high levels of CCL2, CXCL1 and CXCL5, compared to VEGF." (PMID 22125641, 2011). "In addition, CXCR2 ligands such as CXCL1 can induce autophagy-driven degradation of MHC class I molecules, as observed in colorectal cancer models, reducing the ability of immune cells to recognize and eliminate tumor cells." (PMID 40427171, 2025). "It has been shown that primary colorectal cancer cells secrete VEGF-A and stimulate TAMs to produce CXCL1 in primary tumors, while in tumors of mice treated with chemotherapy, TAMs accumulate around the blood vessels and promote tumor revascularization and recurrence by releasing VEGF-A." (PMID 36434686, 2022). "As a potential biotherapeutic target for colorectal cancer, the mechanism by which CXCL1 affects the development of colorectal cancer is not clear." (PMID 36434686, 2022). "The function of CXCL1 is mainly mediated by G protein-coupled receptor CXCR2 binding, and TCGA database analysis shows that there is a high positive correlation between CXCL1 and CXCR2 RNA expression in colorectal cancer." (PMID 36434686, 2022). "The human colorectal cancer-derived HCT116 cell line has been shown to upregulate CXCL8 (IL-8) and CXCL1 in response to F. nucleatum ATCC 23726 and may contribute to metastatic spread." (PMID 34700376, 2021). "Therefore, the CXC family plays an important role in the development of colorectal cancer, especially CXCL8, CXCL3, and CXCL1." (PMID 32462020, 2020). "In addition, CXCL1 and CXCL8 promote the migration of colorectal cancer cells." (PMID 39595551, 2024).
colorectal cancer (continued). "Subsequently, we analyzed CXCL1 expression profiles in the GEPIA database and TIMER 2.0 database, and based on expression data in the databases, we determined that CXCL1 expression was significantly higher in human colorectal cancer tissues than in paratumoral normal tissues." (PMID 36434686, 2022). "However, the specific mechanism of action of CXCL1 in colorectal cancer is not well characterized." (PMID 36434686, 2022). "Also, chrysin and daidzein decreased CXCL1 and MMP-9, essential molecules released by the TME that facilitate tumor progression in the rat model of colorectal cancer; therefore, chrysin and daidzein have potential in preventing colorectal cancer angiogenesis and metastasis." (PMID 34950252, 2021). "With in situ mRNA hybridization CXCL1 was also found to be an upregulated transcript in colorectal cancer FFPE tissues, with no CXCL1 ISH signal in the healthy and adenomatous colon tissue specimens." (PMID 26208990, 2015).
COVID-19 (75 papers, 2020 to 2025). A disease caused by infection with severe acute respiratory syndrome coronavirus 2. "In COVID-19 patients, CXCL1 binds to CXCR2 to promote immune cell chemotaxis, causing a cytokine storm that worsens the symptoms of patients." (PMID 35185890, 2022). "In our study, interleukins (IL-1 α, IL-7, IL-17, and IL-18) and chemokines (CCL11 and CXCL1) were found increased in COVID-19-only." (PMID 41516165, 2025). "Delivery of these complexes to uninfected mice boosts plasma interleukin-6 and CXCL1 levels as observed in COVID-19 patients." (PMID 38306481, 2024). "Concentrations were significantly higher in the COVID-19+ cohort except for IL-1β, CXCL1, IL-10 and CXCL8." (PMID 38715114, 2024). "The box diagram showed that the expression levels of CXCL1 in symptomatic COVID-19 cases with myocardial injury were significantly higher than those in uninfected healthy individuals and asymptomatic COVID-19 cases (P<0.05)." (PMID 37564653, 2023). "The myocardial injury caused by COVID-19 was associated with multiple inflammatory pathways, and IL6, NFKBIA, CSF1, CXCL1, IL1R1, SOCS3, and CASP1 were key genes of the inflammatory pathway." (PMID 37564653, 2023). "CXCL1 also causes the recruitment of neutrophils to the lungs and so an increase in respiratory CXCL1 levels leads to an increase in neutrophils in the BAL fluid of patients with COVID-19." (PMID 36613652, 2022). "In fact, of the 13 most abundant mediators in BAL fluid of severe COVID-19 subjects, 11 were chemokines, with CXCL1 and CXCL8 being 200 times more abundant than IL-6 and TNF-α." (PMID 35812400, 2022). "The disease is also associated with the elevated blood levels of other chemokines such as CCL2/MCP-1, CCL3/MIP-1α, CCL4/MIP-1β, CXCL9/MIG, CXCL10/IP-10 and CX3CL1/Fractalkine, which shows that CXCL1 is only one of many COVID-19 factors." (PMID 36613652, 2022). "With regards to circulating chemokine levels, CCL3, CXCL9, CCL20, and CXCL1 were significantly upregulated in samples from individuals with severe COVID-19 when compared against mild and moderate cases." (PMID 34957382, 2022). "In the blood of patients with moderate and severe coronavirus disease 2019 (COVID-19) there are elevated levels of CXCL1 and CXCL8/IL-8." (PMID 36613652, 2022). "Of the proinflammatory cytokines, the following are of particular interest: CCL20, which has been associated with the first severe acute respiratory syndrome coronavirus (SARS-CoV), and IL-1B, CXCL1, CXCL2, and CXCL8, which are associated with COVID-19." (PMID 32752138, 2020). "The AR regulates two chemotactic factors, the chemokine (C-X-C motif) ligand-1 (CXCL1) and chemokine (C-C motif) ligand-20 (CCL20), which are encoded by COVID-19-induced genes." (PMID 32600476, 2020). "The study found that 2 of the COVID-19 induced genes (neutrophil chemotactic factor CXCL1 and the predominantly dendritic cell chemotactic factor CCL20) undergo regulation by androgen receptors." (PMID 33117174, 2020). "Additionally, the concentrations of CXCL1 and CXCL10 in the epithelial lining fluid (ELF) were also elevated in the COVID-19-associated ARDS." (PMID 38745657, 2024). "Our results suggested that disruption of the CXCL5 and CXCL1/2 axis may be important early components of the inflammatory dysregulation that is characteristic of severe cases of COVID-19." (PMID 34835277, 2021). "However, the exact expression of ELANE, ARG1, and CXCL1, as well as neutrophil counting in COVID-19 patients, should be investigated by further studies to shed further light on COVID-19 treatment." (PMID 32582303, 2020). "A previous study showed that the systemic concentrations of neutrophil chemokines (CXCL1/8), myeloperoxidase levels, and nasal IL17D transcription are correlated with the functional severity of COVID-19." (PMID 40362649, 2025). "The interaction between the CXCL family (CXCL1, CXCL2, and CXCL8) is also considered a COVID-19 severity-specific molecular interplay." (PMID 40163554, 2025).
COVID-19 (continued). "The main inflammatory cytokines and chemokines widely produced by patients with severe forms of COVID-19 are IL-6, IL-8, IL-1β, TNF-alpha, IFN-gamma, MIP1α and 1β, CCL2, CCL5, CCL20, CXCL1, CXCL2, CXCL8, CXCL10, and CXCL17." (PMID 39768136, 2024). "We performed a study using peripheral blood mRNA-seq data from 41 COVID-19 patients to obtain the immune-characterized genes of COVID-19 severe disease, namely, the hub genes (FPR1, FCGR2A, TLR4, S100A12, CXCL1, and LTF)." (PMID 38674681, 2024). "CXCL1 is a chemoattractant for neutrophils, the infiltration of which in the lungs can drive ARDS in COVID-19." (PMID 38306481, 2024). "Based on the Degree, MCC, Closeness, Betweenness, and MNC algorithms of the CytoHubba plug-in, six genes (FPR1, FCGR2A, TLR4, S100A12, CXCL1, and LTF) were confirmed as hub genes related to COVID-19 severe." (PMID 38674681, 2024). "High levels of these molecules, detected after macrophage treatment with VLPs (TNFα, IL-1β, CCL8, CXCL8, CXCL9, CXCL16, CXCL1, and CXCL2), were shown to correlate with severe COVID-19 in other studies." (PMID 38664730, 2024). "In male individuals suffering from COVID-19 it was observed that five inflammatory proteins were significantly higher abundant: OPG, AXIN1, CXCL1, CCL11 and CCL10." (PMID 37832397, 2023). "Further, they observed that key driver genes, which were upregulated with COVID-19 and IBD inflammation (e.g., CXCL1, GBP4, SOCS3, PARP14, and PARP9), were downregulated following the use of infliximab." (PMID 36060521, 2022). "A higher expression of chemokines (CXCL1, CXCL2, CXCL3, CXCL8 and CXCL16) were also found in the CD4+ TCM and Classical Monocytes in the COVID-19 patients." (PMID 36532041, 2022). "In large airway tissues, genes related to the mucosal layer (MUC4, MUC5AC, MUC5B) as well as cytokine-mediated signaling pathway genes (CCL20, CXCL1, CXCL6, CXCL6, MMP1) and type I interferon genes (IFIT3, ISG15, STAT1, MX1) were upregulated in COVID-19." (PMID 35233546, 2022). "COVID-19 immune response and SZ share one DEG (activin A receptor type II-like 1, or ACVRL1) that is upregulated and two DEGs (CXCR2, CXCL1) that are both downregulated, all of which are strongly associated with the pathogenesis of COVID-19." (PMID 35185890, 2022). "Our study also found 4 additional targets (CCL20, CSF3, CXCL1, CXCL10) with existing therapies that have yet to be trialed in the COVID-19 patient population." (PMID 34582497, 2021). "CXCL1 and CXCL2 have appeared to be heavily involved and modulated by exposure to the COVID-19 virus." (PMID 33117174, 2020). "A trend toward higher ELF concentrations of CXCL1 (p = 0.287), CXCL10 (p = 0.287), granzyme B (p = 0.110), TRAIL (p = 0.094), and EGF (p = 0.094) is observed in COVID-19 patients." (PMID 33138839, 2020). "Increased levels of interleukins (IL-1 α, IL-7, IL-17, and IL-18) and chemokines (CCL11, and CXCL1) were found only in the COVID-19-only, whilst PLWH/COVID-19, had increased levels of four different interleukins (IL-5, IL-6, IL-9, and IL-15) and one chemokine (CXCL10) compared to COVID-19-only." (PMID 41516165, 2025). "Additionally, we found other mediators of neutrophil recruitment, such as CXCL1, as well as NFKB1, which is important for innate immune response and inflammation activation, to be downregulated in COVID-19 (+) tissues." (PMID 38932146, 2024). "In this study, we used mRNA-seq data from the peripheral blood of COVID-19 patients to identify six COVID-19 severe immune characteristic genes (FPR1, FCGR2A, TLR4, S100A12, CXCL1, and L TF), and found neutrophils to be the critical immune cells in COVID-19 severe disease." (PMID 38674681, 2024). "COVID-19 ICU patients had significantly higher levels of the proinflammatory cytokines CXCL1, IL-1β, IL-6, MCP-1, and TNF-α compared to the non-COVID group." (PMID 35502320, 2022).